MAFA (MAF bZIP transcription factor A)
Diseases named in the same sentence as MAFA in open-access papers (continued):
Sharing a sentence is not in itself a finding about the gene and the disease.
Hyperglycemia (24 papers, 2012 to 2025). An increased concentration of glucose in the blood. "In islets isolated from diabetic db/db mice, MafA is decreased due to hyperglycemia-associated oxidative stress and c-Jun activity." (PMID 35454124, 2022). "The phenotype of MafA-deficient adult mice showed reduced expression of insulin secretion genes, fasting hyperglycemia, and impaired glucose-stimulated insulin secretion." (PMID 31208980, 2019). "In mice from the ICR strain, a deficiency of MafA contributed to fasting hyperglycemia at an early stage of adulthood." (PMID 31208980, 2019). "The loss of Glut2 and MafA in islets of db/db mice can be reversed when hyperglycemia is corrected, so it would be interesting to investigate if the derepression of the disallowed genes can also be reversed." (PMID 28792951, 2017). "Thus, we confirm a defect in a crucial regulatory region of the MAFA protein as an important cause of a specific hereditary syndrome, which is characterized by insulinomatosis and/or mild hyperglycemia." (PMID 35406570, 2022). "Thus, chronic hyperglycemia in β-cells increases oxidative stress and causes β-cell dysfunction due to decreased MafA and Pdx-1." (PMID 33918379, 2021). "Nevertheless, under metabolically stressful conditions like hyperglycaemia or lipotoxicity, it has been shown that MafA expression paradoxically decreases." (PMID 38745946, 2024). "We, thus, confirm MAFA phosphorylation defects as an important cause of a hereditary syndrome, which is characterized by insulinomatosis and/or mild, MODY-like hyperglycemia." (PMID 35406570, 2022). "MAFA expression is altered in response to pathological states such as oxidative stress and hyperglycemia in human islets, however its role in regulating cytokine signaling in the islet has not yet been studied." (PMID 30567413, 2018). "Adenoviral delivery of Ngn3, Pdx1 and MafA in vivo has been shown to reprogram acinar cells and other cells of the gastrointestinal tract into β-like cells that can ameliorate hyperglycaemia in an experimental animal model of diabetes." (PMID 30337647, 2018). "In this context, we have hypothesized that beta cells are in a compensatory state due to hyperglycaemia in which TAC accelerates the dysregulation of transcriptional factors like MafA." (PMID 38745946, 2024). "Chronic hyperglycemia gradually decreases insulin biosynthesis and secretion which is accompanied by reduced expression of very important insulin gene transcription factors MafA and PDX-1." (PMID 37720599, 2023). "It has been shown that chronic hyperglycemia gradually decreases insulin biosynthesis and secretion which is accompanied by reduced expression of very important insulin gene transcription factors MafA and PDX-1." (PMID 37720599, 2023). "However, a combination of the three transcription factors, ngn3, MafA and pdx1, converted the acinar cells into beta-like cells and improved hyperglycemia in toxin-induced-diabetic mice." (PMID 34882233, 2021). "Downregulation of FOXO1 may be caused by chronic hyperglycemia‐induced oxidative stress; consequently, β‐cell fate cannot be maintained, due to insufficient β‐cell transcription factors, PDX1, MAFA, and NKX6.1, all of which are FOXO1‐dependent." (PMID 33312555, 2020). "Similarly, in islets of diabetic KKAy mice, the number of c-Jun-positive cells was increased with marked hyperglycemia, and both MafA and insulin protein levels were decreased in those cells." (PMID 25794287, 2015). "Similarly, in obese diabetic KK-Ay islets, the number of c-Jun-positive cells was increased with marked hyperglycemia, and both MafA and insulin protein levels were decreased in those cells." (PMID 23202973, 2012). "Expression of several β-cell (Pdx-1, MafA, Nkx6.1 and Glut2) and α-cell (Arx, Pax6 and MafB) markers was examined to determine whether the molecular identity of islet cells was altered by exposure to chronic hyperglycaemia." (PMID 25145789, 2014).
Hyperglycemia (continued). "Among these, so-called “resistant” β-cells maintain high INS, MAFA, and PDX1 expression under diabetic conditions, preserving function despite hyperglycemia and inflammation." (PMID 41584842, 2025). "A well-known combination of factors - Pdx1, Ngn3, and MafA (PNM) has been shown to convert exocrine cells into insulin-producing β-like cells, ameliorating hyperglycemia in mice." (PMID 41584842, 2025). "We have also found that MafA knockout, MafB heterozygote (A0B1) adult mice display more severe hyperglycemia than do A0 adult mice." (PMID 31208980, 2019). "In this regard, a direct contribution of an altered expression of transcription factors involved in the maintenance of β-cell identity (e.g. PDX1, NKX6.1, MAFA or NEUROG3, among others) has been proposed to explain β-cell failure under pathological conditions of hyperglycemia and lipotoxicity." (PMID 37274331, 2023). "Under diabetic conditions, hyperglycemia per se and subsequent induction of oxidative stress decrease insulin biosynthesis and secretion, accompanied by reduction in expression and/or activities of insulin gene transcription factors PDX-1 and MafA." (PMID 23202973, 2012). "Mice specifically lacking MafA in β cells demonstrated broad, population-wide changes in hormone gene expression with an overall gene signature closely resembling islet gastrin+ (Gast+) cells generated under conditions of chronic hyperglycemia and obesity." (PMID 37606041, 2023). "In addition, db/db mice with hyperglycemia had increased levels of pancreatic β-cell dedifferentiation independently of blood lipid levels; their pancreatic islets had decreased levels of mature β-cell markers such as GLUT2, Pdx-1, MafA and Nkx6.1." (PMID 33918379, 2021).
type 2 diabetes (20 papers, 2013 to 2025). "With loss of MAFA in type 2 diabetes, β-cells cannot maintain their mature phenotype and are dedifferentiated." (PMID 35562869, 2022). "Since synthesis of non–β cell hormones appears to be negatively regulated by human MAFB and is associated with the loss of β cell identity and activity postnatally in type 2 diabetes (T2D), we examined here how MAFA and/or MAFB contributed to this process in adult mice and human islets." (PMID 37606041, 2023). "Type 2 diabetes is associated with beta cell loss of identity, dedifferentiation or beta to alpha cell transdifferentiation, and can in later stages often result in loss of transcription factors such as MafA, Nkx6-1 and Pdx1." (PMID 34296320, 2021). "They find that MafA, a transcription factor required for beta-cell maturation, directly regulates the gene encoding CaVγ4 and suggest that restoration of CaVγ4 may be a potential treatment for type 2 diabetes." (PMID 30911681, 2019). "It is also noteworthy that detrimental effects on adult β cell activity caused by MafA or MAFB reduction are much subtler than found for other islet-enriched TFs, many of which are associated with maturity-onset diabetes of the young." (PMID 37606041, 2023). "MafA expression is decreased in type 2 diabetes, contributing to β-cell dysfunction and disease progression." (PMID 35454124, 2022). "MAFA is critical for the maintenance of β-cells, and its downregulation results in β-cell dedifferentiation in type 2 diabetes." (PMID 35562869, 2022). "Recently, Butler and colleagues reported that nuclear localization of MAFA was abolished in beta cells of type 2 diabetes patients." (PMID 24013263, 2013). "Moreover, the decrease of MAFA, MAFB, and PDX1 expression levels have been found in human type 2 diabetes islet alpha and beta cells, which can be associated to islet cell dysfunction." (PMID 31405383, 2019). "In contrast, in our 16 week old db/db mice, which is a model for type 2 diabetes, we do observe a severe depletion of mRNA’s that are normally enriched in beta cells (MafA, ZnT8, Glut2), as previously published, together with a loss of expression of islet hormone genes." (PMID 28792951, 2017). "Although some previous studies have reported decreased expression levels of MafA and PDX1 in type 2 diabetes, the present study showed increased expression levels of both factors in STZ-diabetic rats." (PMID 36109786, 2022). "A PCA plot bar graph based on the expression levels of MAFA, NKX6.1, CCT4, XBP1 and GRP78, as well as PDIA1, shows a clearer division between the three groups, highlighting the progression from NGT to IGT and then type 2 diabetes." (PMID 36280617, 2023). "Interestingly, MAFA nuclear expression in both alpha and beta cells, and the percentage of alpha cells expressing PAX4 were found altered in a substantial proportion of patients with type 2 diabetes." (PMID 24013263, 2013).
insulinoma (10 papers, 2011 to 2023). "In 2018, two unrelated families with point mutations in the transcriptional activation domain of the MAFA gene were reported to have familial diabetes and insulinoma." (PMID 37895232, 2023). "Immunohistochemical examinations in patients with MEN1 associated insulinomas demonstrated a linked decrease in both menin and MAFA." (PMID 35406570, 2022). "Another gene was recently associated with the onset of insulinomas, namely the V-Maf avian musculoaponeurotic fibrosarcoma oncogene homolog A (MAFA)." (PMID 30657883, 2019). "MAFA protein expression was found in the nuclei of islet cells as well as in the nuclei of an insulinoma." (PMID 35406570, 2022). "Notably, differences exist between c-MAF- and MAFB-mutant mice and MAFA-mutant mice in terms of their proclivity to develop insulinoma, a typical disease in humans." (PMID 37895232, 2023). "Furthermore, in vitro analysis using insulinoma-derived cell lines revealed that menin regulates MAFA on both protein and mRNA levels and binds to MAFA promoter sequences." (PMID 35406570, 2022). "Moreover, in mouse insulinomas, decreased MAFA expression resulting from targeted MEN1 ablation was consistently observed." (PMID 35406570, 2022). "In order to test whether TAT confers MafA the ability to penetrate across cellular membranes, mouse pancreatic insulinoma cells MIN-6 and β-TC3 were incubated with Alexa Fluor 568-labeled protein (final concentration in culture medium: 1 μM)." (PMID 21857924, 2011). "In insulinoma cell lines, MENIN binds to MafA promoter sequences and transcriptionally regulates MafA protein and mRNA levels." (PMID 36750911, 2023). "The transdifferentiated PANC-1 and MIA PaCa-2 cells expressed 80.63% and 56.1%, respectively, of the INS mRNA levels seen in the insulin-producing human insulinoma cell line NT-3, while the abundance of SLC2A2 and MAFA transcripts was higher and lower, respectively, than in NT-3 cells." (PMID 34572891, 2021). "Moreover, a relationship between MEN 1 and MAFA genes was also established: altered MEN1 expression was shown to disrupt the MAFA differentiation pathway in human and mice insulinoma cells." (PMID 33101198, 2020). "In parallel, we recently demonstrated that one such inhibitor, ORY-1001, could enhance expression of insulin, MAFA, NEUROD, and GK in the insulinoma INS-1E cell line." (PMID 31072002, 2019). "Canonical beta cell transcription factors such as PDX1, NKX6.1, MAFA, and others were not substantially altered in insulinomas vs. beta cells." (PMID 28974674, 2017). "Menin knockdown concomitantly decreased the mRNA expression of both MAFA and β-cell differentiation markers (INS, GCK, SLC2A2, and PDX1) while increasing tumor proliferation, indicating that altered menin expression disrupts the MAFA differentiation pathway in insulinoma." (PMID 35406570, 2022).
Glucose intolerance (7 papers, 2014 to 2025). Glucose intolerance (GI) can be defined as dysglycemia that comprises both prediabetes and diabetes. "Taken together, our data show that GPRC5B helps to maintain a mature β cell phenotype by regulating the cAMP/CREB/MafA pathway and that genetic inactivation of this receptor leads to reduced insulin secretion and glucose intolerance in HFD-fed mice." (PMID 40906536, 2025). "Our studies investigating Notch signaling in β-cells found that forced Notch signaling in β-cells caused MafA degradation, leading to impaired GSIS and thereby glucose intolerance." (PMID 35454124, 2022). "The HFD mice develop glucose intolerance within a week that coincided with reduction in expression of SetD7 along with previously reported decreased expression of MafA, Glut2, Gck, GIPR, and PPARγ in islets." (PMID 34592314, 2021). "A mouse model with MIP1-CreERT-driven β-cell-specific knockout of SetD7 developed glucose intolerance with islet specific downregulation of the critical β-cell genes Pdx1, MafA, Glut2, and Gck." (PMID 34592314, 2021). "Mice lacking MafA display deficient insulin secretion and glucose intolerance postnatally." (PMID 41008194, 2025). "Thus, β-cell-specific Fermt2-knockout mice show reduced islet MafA and impaired GSIS, leading to glucose intolerance." (PMID 35454124, 2022).
Obesity (6 papers, 2013 to 2025). Accumulation of substantial excess body fat. "Orphan receptor GPRC5B maintains mature β-cell function in obesity via cAMP/CREB-dependent MafA regulation; β-cell-specific GPRC5B-knockout mice have reduced insulin secretion and develop a prediabetic condition." (PMID 40906536, 2025). "Taken together, GPRC5B helps to maintain mature β cell function in obesity through cAMP/CREB-dependent regulation of MafA expression." (PMID 40906536, 2025). "In both genotypic and phenotypic models of obesity, Tacrolimus induced a decrease in nuclear MafA and an increase in nuclear FoxO1A." (PMID 38745946, 2024). "We found that MAFA expression was unaltered in islets from subjects with obesity as compared to normal individuals." (PMID 24013263, 2013). "It is noteworthy that MafA mutant mice have a subtler islet phenotype than these other islet-enriched TF mutants, correlating with earlier inducers of β cell dysfunction such as obesity." (PMID 37606041, 2023). "Interestingly, MafA levels are — despite reduced CREB phosphorylation — not yet significantly changed in lean mice, which might indicate that GPRC5B-dependent cAMP/CREB regulation becomes more relevant for MafA regulation during obesity development." (PMID 40906536, 2025). "Realizing that, on a C57BL/6J background, a deficiency of MafA alone was not sufficient to show the possible role of MafB in maintaining adult β-cell function, we implemented HFD treatment for mice to induce obesity and obtain a more severe phenotype." (PMID 31208980, 2019).
type 1 diabetes (4 papers, 2013 to 2023). "Similarly, expressing the transcription factors Pdx1 and MafA in neighboring α cells can convert these cells into functional, insulin-producing β cells that appear resistant to autoimmune destruction in models of type 1 diabetes." (PMID 36706177, 2023).
Insulin resistance (3 papers, 2021 to 2023). Increased resistance towards insulin, that is, diminished effectiveness of insulin in reducing blood glucose levels. "Other than insulin resistance, stability of V-maf musculoaponeurotic fibrosarcoma oncogene homolog A (MafA) protein, which is a β cell-enriched transcription factor that promotes β-cell maturation and function, can also be associated with senescence of β cells." (PMID 35432205, 2022). "As a result, we predict that these associated gene signatures will be induced even earlier than GAST itself upon pathologically induced loss of MafA or MAFB, which could be tested temporally in future studies in models of insulin resistance (i.e., following S961 or high-fat diet treatment)." (PMID 37606041, 2023).
enterovirus infection (2 papers, 2018 to 2023). "In order to evaluate if the loss of MafA altered the immune status of islets, MafA deficient mouse islets (MafA−/−) were assessed for inherent anti-viral response and susceptibility to enterovirus infection." (PMID 30567413, 2018). "For example, MafA, a crucial transcription factor for β-cell function is remarkably decreased in T2D β cells and its reduction leads to critical changes in the β-cell anti-viral response and susceptibility to enterovirus infection." (PMID 38027145, 2023). "MafA deficient islets showed enhanced expression of both Ifnβ1 and Mda5 prior to and post CVB3 enterovirus infection, resulting in reduced virus propagation." (PMID 30567413, 2018).
hypothyroidism (2 papers, 2015 to 2019). Abnormally low levels of thyroid hormone. "It is therefore tempting to speculate that hypothyroidism in Pax8 +/- mice hinders postnatal beta cell maturation with subsequent increased in the susceptibility to stress-induced apoptosis with age, favouring the replacement of beta cells by delta cells that do not require MafA." (PMID 31518338, 2019).
multiple myeloma (2 papers, 2022 to 2023). "The combo treatment strikingly upregulated HERC4 and MafA in the myeloma xenografts compared with the control or the single treatments." (PMID 37028761, 2023). "This is confirmed by the combined treatment of LiCl, the inhibitor of GSK3β, and Dex, a major anti-MM agent, which strikingly upregulate HERC4 and inhibit MafA therefore suppressing MM cell proliferation and myeloma xenograft growth in mice." (PMID 37028761, 2023). "MafA and c-Maf are close members of the Maf transcription factor family and indicators of poor prognosis of multiple myeloma (MM)." (PMID 37028761, 2023). "In the present study, we found that inhibition of GSK3β and induction of HERC4 might inhibit MafA and suppress myeloma cell proliferation and tumor growth." (PMID 37028761, 2023). "In particular, in 8–10% of multiple myelomas the MAF, MAFB, and MAFA genes are translocated to the immunoglobulin heavy chain locus." (PMID 35406570, 2022).
breast carcinoma (1 paper, 2017). "MAFA, another gene, was identified among the top genes present in breast cancer cell lines in this study." (PMID 28607444, 2017).
hyperuricemia (1 paper, 2021). An abnormally high level of uric acid. "Decreased GSIS in hyperuricemia may be due to decreases in MafA protein expression as MafA is a key regulator of insulin secretion in β-cells." (PMID 33593356, 2021).
Hypoglycemia (1 paper, 2014). A decreased concentration of glucose in the blood. "Thus, intestinal expression of Pdx1, MafA, and Ngn3 drives the formation of ectopic insulin-producing cells that confer an improved response to glucose challenge without fasting hypoglycemia." (PMID 24613355, 2014).
maturity-onset diabetes of the young (1 paper, 2022). "It is known that MAFA is a causative gene of maturity-onset diabetes of the young (MODY)." (PMID 35432205, 2022).
pancreatic agenesis (1 paper, 2024). Partial agenesis of the pancreas is characterized by the congenital absence of a critical mass of pancreatic tissue. "Due to the decreased expression of transcription factors that promote endocrine function and pancreas development, PDX1, MAFA, and NKX6.1, pancreatic agenesis is present in 83.6%." (PMID 39596087, 2024).
Zinc deficiency (1 paper, 2023). A deficiency of the essential metal Zinc; an essential cofactor for many enzymes. "Zinc deficiency may cause down-regulation in the key β-cell transcription factors like MafA, Pax6, and Nkx2.2 and lead to β-cell de-differentiation, while vitamin D3 treatment can prevent β-cell de-differentiation and increase the expression of genes of VDR, Pdx1, MafA, and Ins1/2 in MIN6 cells." (PMID 36714968, 2023).